TMEM267 (transmembrane protein 267)
Synonyms: C5orf28; FLJ21657
Tractability: Antibody: UniProt predicts a signal peptide or a membrane-spanning region.
Gene: Protein-coding gene on chromosome 5 (43,444,252 to 43,484,476, reverse strand). Ensembl gene ENSG00000151881.
Subcellular location: Membrane
Subcellular location (Human Protein Atlas): Nucleoplasm; Vesicles
Gene Ontology:
Molecular function: protein binding
Cellular component: membrane
Genetic constraint (gnomAD): Loss-of-function variants: 18 observed, 18.7 expected, observed/expected ratio (o/e) 0.96, 90% interval 0.66 to 1.43. The upper end of that interval is the gene's LOEUF score, 1.43, which puts it in group 5 of 6, group 1 being the genes least tolerant of losing a copy. Missense variants: 232 observed, 261.19 expected, observed/expected ratio (o/e) 0.89, 90% interval 0.8 to 0.99. Synonymous variants: 85 observed, 91.34 expected, observed/expected ratio (o/e) 0.93, 90% interval 0.78 to 1.11.
Homologues: Orthologues: chimpanzee TMEM267 (99% identical), macaque TMEM267 (98% identical), dog TMEM267 (93% identical), pig TMEM267 (92% identical), rabbit TMEM267 (89% identical), guinea pig TMEM267 (86% identical), rat Tmem267 (80% identical), mouse Tmem267 (79% identical), tropical clawed frog tmem267 (74% identical), zebrafish tmem267 (67% identical), Drosophila melanogaster CG10866 (30% identical).
Diseases named in the same sentence as TMEM267 in open-access papers:
TMEM267 is named in the same sentence as 4 diseases in open-access papers, as found by Europe PMC text mining. Sharing a sentence is not in itself a finding about the gene and the disease. The quoted sentences say what the papers report.
cancer (1 paper, 2023). A tumor composed of atypical neoplastic, often pleomorphic cells that invade other tissues. "Among them, five genes (FGG, MYH15, STARD4, SYTL4, and TMEM267) were first associated with cancer procession, while the other three (KRT81, KRT6A, and KRT13) have previously been confirmed to be related to cancer metastasis and migration." (PMID 37817112, 2023).
TMEM267 also shares sentences with these, for which no sentence is quoted: ovarian carcinoma (1 paper); tongue cancer (1); tumor (1).